MYC (MYC proto-oncogene, bHLH transcription factor)
Diseases named in the same sentence as MYC in open-access papers (continued):
Sharing a sentence is not in itself a finding about the gene and the disease.
glioblastoma (continued). "Nevertheless, it remains unclear whether c-MYC is able to transcriptionally regulate expression of LPP-AS2 in glioblastoma." (PMID 32962742, 2020). "Therefore, we demonstrated that LPP-AS2 regulates EGFR expression and activates the PI3K/AKT/c-MYC signaling pathway by competitively sponging miR-7-5p, thereby promoting glioblastoma cell viability." (PMID 32962742, 2020). "Manipulating IMPDH expression in glioblastoma cells results in the same change in MYC expression." (PMID 33322239, 2020). "It was reported that in glioblastomas, glycolytic metabolism is 3 times higher than normal brain tissues, which can be regulated by several oncogenes and tumor suppressor genes, such as c-MYC and HIF-1." (PMID 30115078, 2018). "Since Teneurin-1 did mediate MYC-RHOA-induced responses in glioblastoma, additional Teneurins might operate through a similar mechanism." (PMID 30618566, 2018). "Moreover, we also analyzed the expression of MYC in a large number of clinical glioblastoma specimens (n = 495) in The Cancer Genome Atlas (TCGA) glioblastoma database." (PMID 27409345, 2016). "Determination of c-MYC expression may serve as a prognostic value in glioblastoma, its expression was increased in approximately 70% of the cases." (PMID 25182732, 2014). "EZH2 was reported to positively regulate MYC in glioblastoma cells." (PMID 21941025, 2011). "Our findings indicate that EGR3 promotes glioblastoma GBM cell growth, accompanied by increased expression of two oncogenic regulators, MYC and CDK1." (PMID 40649712, 2025). "However, c-MYC overexpression alone is insufficient to induce a glioblastoma-specific phenotype." (PMID 40917877, 2025). "Thus, targeting HELLS in glioblastoma might offer a viable approach to disrupting the relatively undruggable MYC and E2E3 oncogenic transcription factors." (PMID 36012581, 2022). "We also show that genes whose expression in hypoxia is affected by c-MYC inhibition are able to distinguish the Proneural subtype of glioblastoma multiforme, thus potentially providing a molecular signature for this class of tumors that are the least tractable among glioblastomas." (PMID 27119353, 2016). "In glioblastoma, eccDNAs carrying EGFR drive sustained receptor tyrosine kinase signaling, while in lung cancer, eccDNAs amplify MYC and promote chromosomal instability and cell division." (PMID 41311372, 2025). "Collectively, RBBP6 maintains high MYC expression in GSCs through regulation of CPSF3-dependent alternative polyadenylation, providing a potential therapeutic paradigm for glioblastoma." (PMID 38503731, 2024). "Therefore, targeting the MYC oncogene could be a promising approach for treating glioblastoma." (PMID 37370649, 2023). "Overexpressed miR-429 impedes glioblastoma cell growth and migration and promotes cell apoptosis by downregulating EGFR, BCL2, and MYC, which are several oncogenes of the ERBB pathway." (PMID 37854282, 2023). "Although the significance of IMPDH2 induction and nuclear hypertrophy in the tumorigenesis of glioblastoma has been reported, EBV infection brings about the change quickly by using its transcriptional cofactor, EBNA2, and MYC." (PMID 37409959, 2023). "MYC for cervical cancer, IDH1 for hepatic cirrhosis, MGMT for glioblastoma and CCND1 for anaplastic thyroid cancer were identified as genes with prognostic importance using survival analysis." (PMID 35001007, 2022).
glioblastoma (continued). "Sensitivity to MYCMI-7 correlates with MYC expression in a panel of 60 tumor cell lines and MYCMI-7 shows high efficacy toward a collection of patient-derived primary glioblastoma and acute myeloid leukemia (AML) ex vivo cultures." (PMID 36874405, 2022). "The ATPase Thyroid hormone receptor interactor 13 (TRIP13), usually overexpressed in a myriad of human cancers, promotes glioblastoma migration and invasion by decreasing the transcription of FBXW7 and attenuating its inhibitory effects on c-MYC." (PMID 35515121, 2022). "In glioblastoma, HELLS interacts with the oncogenic transcription factors E2F3 and MYC to support GSC-specific proliferation and maintenance." (PMID 36012581, 2022). "A small molecule C11, which specifically inhibited the IRES activity of c-MYC by blocking the interaction of hnRNP A1 and IRES, exerted a synergistic anti-glioblastoma effect in combination with mTOR inhibitor rapamycin or PP242." (PMID 36365147, 2022). "Similar data have been documented in glioblastoma and lung adenocarcinoma models, where antiproliferative effects and transcriptional changes by BET inhibition occur at unchanged MYC/MYCN levels." (PMID 33668642, 2021). "The oncogenic roles of HELLS in glioblastoma are likely mediated through interactions with E2F3 and MYC." (PMID 34315468, 2021). "In glioblastoma, in contrast to its proposed role, YTHDF2 was shown to stabilize MYC and VEGFA to maintain the oncogenic phenotype of glioblastoma stem cells." (PMID 33795663, 2021). "ChIP was performed to prove that c-MYC specifically binds to the promoter of LPP-AS2 and elevates LPP-AS2 expression in glioblastoma." (PMID 32962742, 2020). "Other embryonic stem cell factors such as OCT4, SOX2, MYC, and KLF4 are also found differentially expressed in glioblastoma and normal neural stem cells." (PMID 33182324, 2020). "MYC and IMPDH expression significantly correlated and IMPDH overexpression has been observed in several cancers, including glioblastoma, leukemia, colorectal cancer, and small cell lung cancer." (PMID 33322239, 2020). "Many of the genes identified through this meta-analysis have in fact been implicated in development of astrocytoma including EGFR (amplification occurs in ∼40% of primary glioblastomas, HIF-1α, MYC, WNT5A, and IDH3A." (PMID 23737970, 2013). "In glioblastomas (GBM), BET inhibitor treatment decreases MYC expression only in a subset of patient-derived models and exogenous MYC expression partially rescues BET driven anti-proliferative effects." (PMID 24293458, 2013). "Similarly, in glioblastoma, miR-92b targets FBXW7 and TRIP13 suppresses its transcription, thereby stabilizing oncogenic proteins like c−MYC and driving tumorigenesis." (PMID 40370434, 2025). "In addition, YTHDF2 can maintain oncogene MYC and VEGFA transcripts in glioblastoma stem cells, thereby offering a therapeutic opportunity in glioblastoma." (PMID 40986143, 2025). "In line with our results, MYC modulation has been identified as a molecular readout of HDAC inhibition in acute myeloid leukemia cells, and the inhibition of MYC transcription by panobinostat has recently been described in glioblastoma models as well." (PMID 39529166, 2024). "In glioblastoma CSCs, YY1 mediates self-renewal through regulation of the SENP1/METTL3/MYC axis." (PMID 37444616, 2023). "In our present study, we connect these independent findings identifying that IL-11Rα expression correlates with both increased c-MYC and GLUD1 expression in glioblastoma patient tumor tissue and enhanced glutaminolysis leading to significantly greater survival in glucose-starved conditions." (PMID 36834778, 2023).
glioblastoma (continued). "Also, YTHDF2 was found to stabilize MYC and VEGFA transcripts in glioblastoma stem cells in an m6A-dependent manner." (PMID 35526051, 2022). "MYC-induced repression of CDK18, as well as ATR inhibition, affects ATR activity, and increases sensitivity to PARPi, thus representing a promising therapy for glioblastoma and, potentially, other PARPi-refractory tumors." (PMID 34201047, 2021). "Furthermore, in glioblastoma multiforme (GBM) cancer cells, highly expressed L1CAM was previously found to increase DNA damage checkpoint activation by NBS1 upregulation via c-MYC 3 h after radiation, resulting in radioresistance." (PMID 34078883, 2021). "Also, c-MYC and MYCN amplification is a predictive biomarker for PARP inhibitor sensitivity in glioblastoma." (PMID 33134168, 2020). "In glioblastoma, PRMT5 activity conferred therapeutic resistance to mammalian target of rapamycin (mTOR) inhibitors by mediating the methylation of heterogeneous nuclear ribonucleoprotein 1 (hnRNP A1) to promote the translation of cyclin D1 and c-MYC, leading to drug resistance." (PMID 39703687, 2024). "However, their overexpression was observed to repress the cell proliferation and migration, and invasion of GBM through downregulating the IGF2BP1 levels, which reduces the level of c-MYC, CD44, MKI67, and PTEN mRNA in GBM cells or blocks G1/S transition in glioblastoma cell." (PMID 29954406, 2018). "In glioblastoma multiforme (GBM), inhibition of EZH2 by S-adenosylhomocysteine hydrolase (SAH) inhibitor 3-deazaneplanocin A (DZNep) was able to reduce self-renewal and tumor-initiating capabilities of GBM CSCs in vivo via affecting transcriptional regulation of oncogene MYC." (PMID 28148257, 2017). "The converse relationship of MC-let-7a-1~let-7d and MYC was only observed in HCC samples (Pearson = 0.408, p = 0.004), but not in normal liver samples (Pearson = −0.066, p = 0.532), normal brain samples (Pearson = −060, p = 0.785) or glioblastoma samples (Pearson = 0.181, p = 0.106)." (PMID 27409345, 2016). "Functional studies in pancreatic ductal adenocarcinoma and glioblastoma demonstrate that MED30 is oncogenic and serves as a prognostic marker independent of MYC amplification." (PMID 42275218, 2026). "Our study demonstrates that TRIM25 promotes glioblastoma cell growth and invasion by regulating the PRMT1/c-MYC pathway through mediation of the splicing factor NONO." (PMID 38303029, 2024). "In glioblastoma, however, we have not detected any remarkable effects of SOX1 silencing on difference in the expression of β-catenin and its downstream target MYC at a cellular level in vitro, in tumors in vivo, as well as in clinical biopsies." (PMID 28425506, 2017). "Unexpectedly, MYC and PTB genes were high in proneural glioblastomas where PKM1 but not PKM2 was highly expressed." (PMID 24077665, 2014). "Using RT-PCR, we confirmed that among the microvesicular transcripts shared by SW480 and glioblastoma microvesicles but not detected in mast cell microvesicles, RAB13, CXCR4, MYC, and FAS transcripts were present in the SW480-derived microvesicles." (PMID 19930720, 2009).
acute myeloid leukemia (273 papers, 2008 to 2026). Acute myeloid leukemia (AML) is a group of neoplasms arising from precursor cells committed to the myeloid cell-line differentiation. "Research in Clinical Cancer Research showed that HDACis cause MYC protein to become acetylated which leads to reduced MYC expression and apoptosis pathway activation in acute myeloid leukemia cells." (PMID 40959208, 2025). "For example, in a tet-off mice acute myeloid leukemia model, introduction of doxycycline lead to suppression of transgenic MYC expression and caused regression of the tumor." (PMID 25612309, 2015). "Similarly, in METTL3-deficient acute myeloid leukemia cells, c-MYC, Bcl-2, and PTEN protein levels were reduced despite a 2-5 log2-fold increase in mRNA expression." (PMID 38385075, 2024). "In acute myeloid leukemia cells, the ectopic expression of miR-99a resulted in increased colony formation, cell proliferation, and chemoresistance by upregulating genes associated with stem cell maintenance, cell cycle, and MYC target genes." (PMID 30396333, 2018). "Many cases of acute myeloid leukemia (AML) with dmin are associated with myelodysplasia and treatment-related diseases; moreover, they are linked to MYC and MLL amplification as well as complex karyotypes." (PMID 40932956, 2025). "In contrast, high levels of H3K27ac marks were observed in a more distal 3′ region termed the BRD4-dependent MYC enhancer (BDME), which has been implicated in regulation of MYC in acute myeloid leukemia (AML) and in GSI-resistant cortical T-ALL." (PMID 27148573, 2015). "The binding of HHT to NKRF disrupts the translocation of p65 and its binding to the MYC promoter, resulting in the downregulation of MYC transcriptional expression, subsequently suppressing the growth of t acute myeloid leukemia (AML) cells." (PMID 39949739, 2025). "It stabilizes G4 structures and downregulates c-MYC expression in acute myeloid leukemia (AML) cells." (PMID 40333779, 2025). "Delving deeper into the mechanism, we identified RRP9—an essential gene for ribosome biogenesis and a key player in acute myeloid leukemia prognosis—as a critical component of the MYC pathway." (PMID 40781078, 2025). "For example, in acute myeloid leukemia (AML), intrinsic resistance to BET inhibition results in activation of a c-MYC enhancer that compensates for the loss of BRD4 by utilizing WNT signaling to drive oncogenesis." (PMID 38654040, 2024). "Another relevant study revealed that METTL3 regulates the expression of oncogenic MYC in acute myeloid leukaemia through m6A modification." (PMID 39247584, 2024). "Two NFATc2-related axes control cancer progression: the NEDD4/FBP1 axis in cholangiocarcinoma and the MYC/NFATc2 axis in acute myeloid leukemia (AML) cells." (PMID 39822413, 2024). "It has been reported that 10058-F4 downregulates the expression of the c-MYC protein in acute myeloid leukemia." (PMID 37111592, 2023). "In contrast, YBX1 promotes mRNA decay of MYC in an m6A-dependent manner to maintain the viability of acute myeloid leukemia cells." (PMID 37345125, 2023). "The formation of Myelocytomatosis (MYC)-containing DMs in acute myeloid leukemia (AML) is recent proof of the episome concept." (PMID 35614494, 2022). "It was found that METTL3 and METTL14 (writers) served an oncogenic role in acute myeloid leukemia (AML) in an m6A manner by promoting the translation of MYC, MYB, BCL2, SP1, and PTEN." (PMID 36281789, 2022). "Bone marrow (BM) microenvironment substantially limits downregulation of mTOR and MYC pathway in FLT3-ITD acute myeloid leukemia (AML) cells upon FLT3 inhibition in vitro and in vivo." (PMID 36259537, 2022). "RBM25, TARDBP, and CELF1 were found to be correlated with many CASEs, among which RBM25 was thought to inhibit the progression of acute myelogenous leukemia by affecting MYC activity." (PMID 35126520, 2022). "Nearly all indicated that in both chronic and acute myeloid leukemia, MYC can impact progression and prognosis of the disease." (PMID 34372899, 2021).
acute myeloid leukemia (continued). "The presence of dmins has been observed in patients with myelodysplastic syndrome, acute myelogenous leukemia or chronic myelomonocytic leukemia, and amplification of the MYC and MLL genes is observed in almost all cases." (PMID 34496008, 2021). "Previous studies showed that triptonide induces cellular senescence and apoptosis by suppressing transcription of TERT and oncogenic c-MYC in acute myeloid leukemia cells." (PMID 33510281, 2021). "Splicing regulator RBM25 was identified as a tumor suppressor in acute myeloid leukemia, and the low level of RBM25 was associated with high MYC activity and poor prognosis of patients." (PMID 34386035, 2021). "Activation of the oncogene MYC is a key driver for acute myeloid leukemia (AML), and is driven by a cluster of enhancers which activity is negatively regulated by the nuclear receptor NR4A." (PMID 34414418, 2021). "M1AP is highly expressed in several cancers, though, a positive correlation between M1AP and MYC was observed only in human acute myeloid leukemia." (PMID 32411526, 2020). "It is over-expressed in cervical cancer, promotes MYC expression and cell proliferation in acute myeloid leukemia." (PMID 32298288, 2020). "Understanding the function and full characteristics of CEBPA and c-MYC genes in the group of patients with acute myeloid leukemia can be particularly helpful in assessing prognosis, and their usefulness as prognostic factors can be revealed." (PMID 33170359, 2020). "METTL14 regulates mRNA stability and the translation of MYB and MYC genes, players in the self-renewal and differentiation of normal HSCs and acute myeloid leukemia (AML) cells." (PMID 32916783, 2020). "Certain types of hematologic cancer cells (e.g., acute myeloid leukemia cells) require BRD9 to sustain MYC transcription, cell proliferation, and a block in differentiation." (PMID 30760718, 2019). "Inversely, Li and coworkers reported a positive regulation of SIRT1 by the c-MYC pathway in acute myeloid leukemia." (PMID 29383100, 2017). "c-MYC has been shown to be involved in drug resistance in MM and other hematologic malignancies such as acute myeloid leukemia (AML)." (PMID 27494872, 2016). "c-MYC is frequently activated in acute myeloid leukemia (AML), and plays an important role in the induction of leukemogenesis." (PMID 26517351, 2015). "The transduction of MYC-deleted library into mouse bone marrow cells and subsequent transplantation induced acute myeloid leukemia in all the host mice within 6 to 15 weeks." (PMID 26606454, 2015). "H3K27ac super-enhancer landscapes near MYC showed a pattern previously reported in acute myeloid leukemia (AML) that is sensitive to BRD4 inhibitors, and in line with this ETP-ALL blasts downregulated MYC in response to the BRD4 inhibitor JQ1." (PMID 27148573, 2015). "Moreover, TTC5 is a MYC interactor in acute myeloid leukemia stem cells, preventing excessive accumulation of MYC." (PMID 41211440, 2025). "Despite the established acentric nature of DMs, we documented the emergence of ectopic centromeres (neocentromeres) in them, increasing their size towards small ring chromosomes in a portion of tumor cells in the bone marrow of Acute Myeloid Leukemia (AML) patients with MYC-DM amplifications." (PMID 37372484, 2023). "Notably, in the pan-cancer gene expression analysis, we found that hnRNP H and F expression show the opposite correlation with MYC in acute myeloid leukemia (LAML) than what is seen in other tumor types." (PMID 37399401, 2023). "In a mouse xenograph model, Dihydroergotamine could suppress the growth of MYC-dependent human acute myeloid leukaemia, and in this study, MYC was the most statistically repressed gene by Dihydroergotamine." (PMID 37193964, 2023).